MAP2 (microtubule associated protein 2)
Description:
The exact function of MAP2 is unknown but MAPs may stabilize the microtubules against depolymerization. They also seem to have a stiffening effect on microtubules.
Synonyms: MAP-2; MAP2A; MAP2B; MAP2C
Tractability: Small molecule: a high-quality ligand is known. Antibody: its Gene Ontology location is reachable by antibodies, with high confidence; the Human Protein Atlas places it where antibodies can reach. PROTAC: ubiquitination databases record sites on it; its protein half-life has been measured; a small molecule that binds it is known.
Target class: Other cytosolic protein
Gene: Protein-coding gene on chromosome 2 (209,423,988 to 209,734,235, forward strand). Ensembl gene ENSG00000078018.
Subcellular location: Cytoplasm, cytoskeleton; Cell projection, dendrite
Subcellular location (Human Protein Atlas): Cytosol; Plasma membrane; Primary cilium; Primary cilium tip
Gene Ontology:
Molecular function: dystroglycan binding; protein binding; microtubule binding; microtubule stabilizing activity; structural molecule activity; tau protein binding; tubulin binding
Biological process: central nervous system neuron development; dendrite morphogenesis; neuron projection development; dendrite development; microtubule cytoskeleton organization; negative regulation of axon extension; negative regulation of microtubule polymerization; positive regulation of anterograde dense core granule transport; positive regulation of anterograde synaptic vesicle transport; regulation of microtubule polymerization; regulation of microtubule-based movement; regulation of organelle transport along microtubule; regulation of protein localization
Cellular component: apical distal dendrite; axon; axon hillock; axon initial segment; basal dendrite; cytoplasm; cytosol; dendrite; dendrite cytoplasm; dendritic branch; dendritic filopodium; dendritic growth cone; dendritic shaft; distal dendrite; main axon; microtubule associated complex; microtubule cytoskeleton; neuron projection; neuronal cell body; primary dendrite; proximal dendrite; proximal neuron projection; apical dendrite; CA3 pyramidal cell dendrite; cell body; and 3 more
Genetic constraint (gnomAD): Loss-of-function variants: 10 observed, 126.93 expected, observed/expected ratio (o/e) 0.0788, 90% interval 0.048 to 0.13. The upper end of that interval is the gene's LOEUF score, 0.13, which puts it in group 1 of 6, group 1 being the genes least tolerant of losing a copy. Missense variants: 2,006 observed, 2,195 expected, observed/expected ratio (o/e) 0.91, 90% interval 0.88 to 0.95. Synonymous variants: 747 observed, 785.06 expected, observed/expected ratio (o/e) 0.95, 90% interval 0.89 to 1.01.
Homologues: Orthologues: chimpanzee MAP2 (99% identical), macaque MAP2 (98% identical), pig MAP2 (89% identical), rabbit MAP2 (88% identical), dog MAP2 (85% identical), mouse Map2 (81% identical), rat Map2 (80% identical), guinea pig Map2 (24% identical), tropical clawed frog map2 (23% identical). Paralogues in human: MAPT (14% identical).
Diseases named in the same sentence as MAP2 in open-access papers:
MAP2 is named in the same sentence as 160 diseases in open-access papers, as found by Europe PMC text mining. Sharing a sentence is not in itself a finding about the gene and the disease. The quoted sentences say what the papers report.
Stroke (47 papers, 2009 to 2025). Sudden impairment of blood flow to a part of the brain due to occlusion or rupture of an artery to the brain. "Computerised reconstructions of immunostained sections map the extent of the neuronal damage (loss of MAP-2 or NeuN signal) and its spatial relation with post-stroke glial (GFAP for astrocytes, Iba1 for microglia, MBP-1 for oligodendrocytes) and vascular (CD31 for endothelial cells) reactions." (PMID 30679481, 2019). "This study comprehensively described MFAP5 after experimental stroke and identified similarities with MAP2 and NF-L." (PMID 40548074, 2025). "The importance of cytoskeletal elements is further strengthened by studies that have shown a correlation of NF-L and MAP2 serum levels with the size of infarction and the clinical outcome in stroke patients." (PMID 40548074, 2025). "When Muse cells were transplanted into a rat stroke model, 65 and 30% of surviving engrafted cells were positive for NeuN and MAP-2, respectively." (PMID 37834052, 2023). "We found that the intensity of MAP2-related immunofluorescence in tissues 24 h after stroke decreased when compared to the contralateral region." (PMID 36151103, 2022). "In vivo, however, human Muse cells took ∼3 days to express early neural markers (Mash1 and NeuroD) and ∼7 days to express maturity markers (MAP2 and NeuN) in the post-infarct tissue of rat stroke model." (PMID 36339573, 2022). "Our preclinical data suggests a high sensitivity of MAP2 to ischemia, which is also reflected by our analyses of human blood samples, as patients suffering from stroke exhibited significantly higher MAP2 serum levels than patients suffering from TIA." (PMID 33931805, 2021). "Another recent study demonstrated that rod-induced microtubule-associated protein-2 (MAP2) degradation and cofilin-mediated apoptosis are reduced if cofilin is inhibited by LIMK1 overexpression in the infarct cortex after stroke." (PMID 34639067, 2021). "The possible use of MAP2 as a stroke biomarker was therefore addressed in comparison to NF-L, which is already conceived as a valuable biomarker for acute neuronal damage." (PMID 33931805, 2021). "This study explores alterations of the cytoskeletal elements NF-L and MAP2 in the setting of stroke in order to evaluate their potential use for neuroprotective approaches and biomarker analyses." (PMID 33931805, 2021). "We further performed MAP2 immunostaining to assess the neuronal dendrites in the stroke areas after viral infection." (PMID 33224952, 2020). "In order to clarify the role of pDCs during the stroke pathology at a later time point, the infarcts were detected at 7 days with MAP-2 stain." (PMID 32076400, 2020). "A small percentage (less than 10% of shh positive cells, total of >100 shh+ cells counted) of these shh expressing cells in the cortical stroke region were MAP2 positive neurons in the ischemic area." (PMID 25927436, 2015). "A trend towards increased Ki67/MAP2-positive cells was observed in the SVZ of AFS cell-transplanted stroke animals compared to vehicle-infused stroke animals (p = 0.0946)." (PMID 22912905, 2012). "MAP2 was also significantly increased in the DG of the AFS cell-transplanted stroke animals compared to vehicle-infused stroke animals (p<0.0001)." (PMID 22912905, 2012). "As circulating levels of NF-L and MAP2 were found to correlate with clinical and tissue-related outcomes in stroke patients, MFAP5 could also be applied as a serum marker that may help to tailor individual treatments." (PMID 40548074, 2025). "The concordance between DTI parameters—particularly FA and RD—and MAP2 staining supports their translational value as non-invasive biomarkers of post-stroke structural recovery and suggests that HxEV treatment fosters a microenvironment favorable to dendritic and axonal repair in vulnerable regions." (PMID 41010360, 2025).
Stroke (continued). "Brain-derived antigens such as myelin basin protein (MBP), myelin oligodendrocyte glycoprotein (MOG), microtubule-associated protein 2 (MAP2), neurofilament light polypeptide (NF-L) and NMDA receptor subunit (NR-2A) have been observed in the CLNs of both mice and humans after stroke." (PMID 38648267, 2024). "Muse cells that homed to the post-infarct area of a stroke model started elongating neurites and expressing progenitor markers NeuroD and Mash1 within 3 days, forming a network-like structure, and expressed maturity markers MAP2 and NeuN at 7 days." (PMID 36339573, 2022). "We also found that severe stroke reduced the total number of vessels by 60%–70% when compared to the contralateral region, while it decreased the number and fluorescence intensity of neuronal-positive cells including NeuN, PV, and MAP2." (PMID 36151103, 2022). "Again, a stroke-mitigating effect was seen at 4 h (MAP2-staining: Ctrl Fab: Med." (PMID 33602266, 2021). "On the other hand, despite its acute sensitivity to ischemic insults and its ischemia-associated degradation by the Ca2+-dependent proteases calpain and caspase, the value of MAP2 as a potential biomarker in the clinical setting of stroke has so far been largely neglected." (PMID 33931805, 2021). "Since remodeling and restored dendrite function can be observed in peri-infarct neurons after stroke, MAP2 serum level alterations might well represent the fraction of moderately, potentially reversibly damaged neurons of the penumbra." (PMID 33931805, 2021). "By quantification of the MAP2- and NF-L-related immunofluorescence intensities in the applied mouse models, the reduction of MAP2-related immunofluorescence intensity in stroke tissue was found to be significant after 4h-p, 24h-t, 24h-p, and 72h-t compared to control regions." (PMID 33931805, 2021). "Isolated stem cells from menstrual blood treated with oxygen-glucose deprivation display neuronal phenotypic markers, such as Nestin and microtubule-associated protein 2 (MAP2) and significantly increase sensorimotor improvement after transplanted into stroke-induced rats." (PMID 34572529, 2021). "Importantly, a direct comparison of NF-L and MAP2 in human blood samples highlights MAP2 as the more sensitive biomarker in stroke patients." (PMID 33931805, 2021). "Thus, MAP2 appears to be a more sensitive stroke biomarker than NF-L, especially for early neuronal damage." (PMID 33931805, 2021). "After stroke, MAP2 signal was largely lost in the control mCherry-infected areas (mCherry columns)." (PMID 33224952, 2020). "hADSCs could transdifferentiate into neuron like cells (MAP2+) in vivo and probably used as seeding cells for replacement based stem cell therapy of stroke." (PMID 25956259, 2015). "Similarly, the number of MAP2 positive cells was significantly increased in AFS cell-transplanted stroke animals compared to the vehicle-infused stroke animals (p<0.01)." (PMID 22912905, 2012). "Similarly, the number of cells labeled with Ki67/MAP2 double-positive cells was significantly increased in the DG of AFS cell-transplanted stroke animals compared to vehicle-infused stroke animals (p<0.001)." (PMID 22912905, 2012). "To investigate stroke‐induced changes in pan‐lactylation across different brain cell types, we performed immunofluorescence co‐staining of pan‐Kla with markers of neurons (MAP2 or NeuN), astrocytes (GFAP or S100β), microglia (IBA1), and oligodendrocytes (Olig2 or MBP)." (PMID 40271828, 2025). "Moreover, immunofluorescence analysis showed that after intravenous injection into C57BL/6 mice at 72 h postischemic stroke, the red fluorescent DiD‐EXO‐PD‐L1‐HGF was co‐localized with glial fibrillary acidic protein (GFAP)‐ or MAP2‐expressing (green fluorescence) cells in the brain with stroke." (PMID 39049677, 2024).
Stroke (continued). "Thus, in the following experiments, the combined information from histological and immunohistochemical staining for neurons (NeuN) and the microtubule-associated protein 2 (MAP2) was used to define the border of the stroke-affected area, which were chosen for the MELC analysis." (PMID 35626695, 2022). "In addition, we previously reported that TMP could increase the expression of microtubule-associated protein-2 (MAP-2) and enhance dendritic plasticity in an experimental stroke model." (PMID 33531914, 2021). "Furthermore, microtubule-associated protein 2 (MAP2), NMDA receptor subunit NR-2A, myelin basic protein (MBP) and myelin oligodendrocyte glycoprotein were found in tonsils and cervical lymph nodes of patients with stroke." (PMID 34572077, 2021). "Therefore, the present study further compares serum levels of MAP2 with NF-L in stroke patients." (PMID 33931805, 2021). "Furthermore, even though a preclinical stroke study could show an increase of MAP2 in the serum of animal subjected to ischemia, the conceivable use of MAP2 as a biomarker in the clinical setting has not yet been addressed." (PMID 33931805, 2021). "Considering the dynamic functions of MAP2 in the growth, differentiation, and plasticity of neurons, especially in dendrites, the presented results suggest that elevated MAP2 serum levels might serve as a biomarker not only for acute neuronal damage but also for neuronal regeneration after stroke." (PMID 33931805, 2021). "LIMK overexpression reduces rod formation, protects synapses, reduces MAP2 degradation, and attenuates cofilin-mediated apoptosis, increasing neuronal survival following stroke and supporting the finding that decreased cofilin activity is beneficial in recovery from strokes." (PMID 34685706, 2021). "Our data showed that treatment of TMP significantly increased MAP-2 expression level in peri-infarct area after stroke and the neurological function was improved meanwhile, indicating that promotion of the reconstruction of dendrites may contribute to the improvements of neurological function." (PMID 26379744, 2015). "In another context, psilocybin, administered post-stroke, improves motor recovery, reduces neuroinflammation, and promotes neuroplasticity by activating the TrkB receptor and increasing levels of BDNF, MAP2, and synaptophysin." (PMID 41369360, 2025). "We analyzed the changes in MAP‐2 expression and discovered that LMW‐ASP significantly upregulated the expression at 28 days after stroke." (PMID 41019183, 2025). "We observed a remarkable reduction in MAP2, RBFOX3, and GAP43 levels in the ET-1 group (all p < 0.01), suggesting a severe axonal injury occurred after stroke." (PMID 39697542, 2024). "Early post-treatment with psilocybin improved locomotor behavior, upregulated the expression of MAP2 and synaptophysin, and down-regulated the expression of IBA1 in the stroke brain." (PMID 39379834, 2024). "In stroke patients, MBP immunoreactivity in the CLNs correlated with larger infarct volumes and poor clinical outcomes, while MAP2 immunoreactivity correlated with smaller stroke volumes and better functional recovery." (PMID 38648267, 2024). "To investigate how perioperative ischemic stroke influences cerebral injury, we established the perioperative stroke model and quantified the brain injury on infarct size by TTC staining and MAP2 staining." (PMID 35799259, 2022). "One day post stroke, MAP2+ cells were scarcely observed after 90-min t-MCAO and p-MCAO, but were present at 56 d post stroke in both models." (PMID 32492968, 2020). "To further evaluate the impact of neuronal specific Mef2c depletion on the ischemic brain injury and post‐stroke neurological functions, we subjected HFD‐treated Mef2cfl/fl or Emx1CreMef2cfl/fl mice to MCAO, and examined the brain injury with MAP2 and IgG double staining and behavioral tests." (PMID 39648651, 2024).
Stroke (continued). "In accordance with previous reports, the ischemic area was defined by the absence of neurons and low expression of MAP2 (i.e., day 3–14 after stroke)." (PMID 35626695, 2022). "Accordingly, significantly increased MAP2 serum levels were observed when comparing TIA patients with patients suffering from stroke, with or without intervention." (PMID 33931805, 2021). "Although NF-L is increasingly established as a clinical stroke biomarker, MAP2 serum measurements after stroke are still lacking." (PMID 33931805, 2021). "Further, the number of MAP2+ neurons in the peri-ischemic areas at 1 d post stroke were not significantly different between the models." (PMID 32492968, 2020). "Quantitative analysis showed that MAP2+ areas were not significantly different between the models at 1 d post stroke, suggesting that early reperfusion did not rescue neurons in peri-ischemic areas." (PMID 32492968, 2020). "A significantly higher number of double-labeled Ki67/MAP2-positive cells and a similar trend towards increased Ki67/MAP2 double-labeling were observed in the DG and SVZ of AFS cell-transplanted stroke animals, respectively, compared to vehicle-infused stroke animals." (PMID 22912905, 2012). "Interestingly, CD63 expression was shown here to be significantly pronounced and co-localized with angiogenic marker VEGF compared to glial marker GFAP or neurogenic marker MAP2, suggesting that the CD63-labeled extracellular vesicles preferably mediated host angiogenesis after stroke." (PMID 38069179, 2023). "Interestingly, the level of MAP2 serum concentrations appeared to be higher in stroke patients with therapies aiming on vessel recanalization than in stroke patients without such treatments." (PMID 33931805, 2021). "A few cells in vehicle-treated stroke rats also expressed Bcl-2 and MAP2 double-labeling, indicating that ischemia alone, without any treatment intervention, might slightly induce the expression of Bcl-2 in neurons." (PMID 19807907, 2009). "Similar to the MAP2+ findings, early reperfusion following 90-min t-MCAO did not affect S100β+ astrocyte survival at 1 d post stroke." (PMID 32492968, 2020). "HF-rTMS applied in the subacute phase of stroke in a rat model did not found changes in the expression of NMDA and MAP-2 around the peri-ischemic area, questioning the role of TMS in synaptic plasticity, LTP, and dendritic plasticity in the early phases of stroke." (PMID 36895285, 2023). "Even though MAP2 serum levels were shown to increase in an animal model of experimental cerebral ischemia and in patients suffering from TBI, clinical data of stroke patients are still lacking." (PMID 33931805, 2021).